KDM6B (lysine demethylase 6B)
Diseases named in the same sentence as KDM6B in open-access papers (continued):
Sharing a sentence is not in itself a finding about the gene and the disease.
infection (14 papers, 2016 to 2025). The state of being infected such as from the introduction of a foreign agent such as serum, vaccine, antigenic substance or organism. "This indicates a conserved KDM6B upregulation and concomitant loss of H3K27me3 in macrophages upon infection with other wild type Salmonella strain SB300 and attenuated aroA mutant." (PMID 34696686, 2021). "KDM6B recruitment upon infection exhibited an associated loss of overall H3K27me3 in host cells and was Salmonella SPI1 effectors coordinated." (PMID 34696686, 2021). "Both GSKJ4 treatment and RNAi mediated KDM6B silencing in our work indicated lowered PPARδ expression and reduced bacterial number at later stages of infection in our in vitro system." (PMID 34696686, 2021). "In our study, infection induced KDM6B-mediated demethylation at the promoter of PPARδ, led to its activation." (PMID 34696686, 2021). "Salmonella-mediated increased expression of KDM6B and global decrease in H3K27me3 levels was synonymous on infection with other wild type (SB300) and attenuated aroA Salmonella mutant (SL3261) strain as can be seen in." (PMID 34696686, 2021). "The Transwell assay also revealed similar results when stable infection by the Lv-sh-KDM6B and transient transfected by the HA-KDM6B overexpression plasmid." (PMID 34001062, 2021). "The identification of KDM6B, a lysine-specific demethylase involved in transcriptional regulation, is particularly noteworthy as it points to the modulation of epigenetic marks during infection." (PMID 40898518, 2025). "Thus, far our data point toward an upregulation of KDM6B and a decrease in H3K27me3 mark during infection of host cells with Salmonella having functional SPI1 loci." (PMID 34696686, 2021). "Post infection KDM6B expression by qRT-PCR and H3K27me3 levels using immunoblots were analyzed." (PMID 34696686, 2021). "Future development of KDM6B inhibitors may reduce the proportion of pro-inflammatory M1 macrophages while enhancing anti-inflammatory M2 macrophage function, thereby diminishing immune rejection and effectively mitigating infection risks." (PMID 41550926, 2025). "Macrophage polarization at late stages of infection upon GSKJ4 treatment and KDM6B RNAi-mediated gene silencing showed impaired M2 polarization in terms of reduced CD301 expressing population in primary BMDMs." (PMID 34696686, 2021). "Importantly, the H3K27 demethylase, lysine demethylase 6B (KDM6B; formerly known as JMJD3), is inhibited by the viral protein product of UL138, a latently expressed protein required for this phase of infection in CD34+ HPCs." (PMID 37439556, 2023).
immune diseases (10 papers, 2017 to 2025). "Previous studies have shown that the H3K27 histone demethylase KDM6B plays a dual role in immune diseases." (PMID 40959109, 2025).
neurodevelopmental disorder (9 papers, 2021 to 2026). A behavioral and cognitive disorder with onset during the developmental period that involves impaired or aberrant development of intellectual, motor, or social functions. "KDM6B, a histone demethylase, is pivotal in gene expression regulation by removing the Polycomb repressive histone marks, and also linked to neurodevelopmental disorders." (PMID 41023738, 2025). "OMIM describes heterozygous KDM6B mutations as a “neurodevelopmental disorder with coarse facies and mild distal skeletal abnormalities”." (PMID 39767643, 2024). "In mice, KDM6B is expressed in the spinal cord during neonatal development, and a recent report indicates that the loss of function of the Kdm6b gene is associated with neurodevelopmental disorders." (PMID 40176294, 2025). "Also, we have identified 15 de novo variants in genes that were previously implicated in ASD or related neurodevelopmental disorders (PHF21A, WASF1, TCF20, DEAF1, MED13, CREBBP, KDM6B,SMURF1, ADNP, CACNA1G, MYT1L, KIF13B, GRIA2, CHM, and KCNK9)." (PMID 38572415, 2024).
metabolic disease (4 papers, 2023 to 2025). A congenital disorder (due to inherited enzyme abnormality) or acquired (due to failure of a metabolically important organ) disorder resulting from an abnormal metabolic process. "KDM6B (also known as JMJD3) has been implicated as an epigenetic regulator in metabolic disorders, including NAFLD, and could specifically serve as a demethylase of histone H3K27." (PMID 37185761, 2023). "Therefore, KDM6B may be promising as an epigenetic target for the treatment of metabolic disorders, which could specifically address lipid levels without affecting glucose levels." (PMID 37185761, 2023).
blood disorders (3 papers, 2022 to 2024). "The multiple roles of KDM6B in various organs or systems make it a potential therapeutic target for some diseases; for example, KDM6B is upregulated in blood disorders, and inhibition of its negative regulator AP-1 in Kdm6b-deficient hematopoietic stem cells restores the functional defects." (PMID 34716527, 2023).
infectious disease (3 papers, 2019 to 2022). A disorder directly resulting from the presence and activity of a microbial, viral, or parasitic agent in humans. "It is mediated by the Jumonji C domain-containing lysine demethylases KDM6A and KDM6B, both of which have been implicated in a wide myriad of diseases, including blood and solid tumours, autoimmune and inflammatory disorders, and infectious diseases." (PMID 35915507, 2022).
bacterial infection (1 paper, 2022). "The results of RT-qPCR and western blot assay showed that KDM6B mRNA and protein expressions in AGS and MKN-45 cells increase with the increase in time of bacterial infection." (PMID 36564369, 2022).
KDM6B also shares sentences with these, for which no sentence is quoted: renal fibrosis (9 papers); acute lymphoblastic leukemia (7); brainstem glioma (4); kidney cancer (4); neurodegenerative disease (4); pancreatic adenocarcinoma (4); testicular germ cell tumor (4); autoimmune disease (3); diabetic nephropathy (3); gastric adenocarcinoma (3); kidney disease (3); non-alcoholic fatty liver disease (3); respiratory failure (3); systemic lupus erythematosus (3); Arthritis (2); bladder cancer (2); cardiomyopathy (2); cardiovascular diseases (2); chronic cystitis (2); chronic kidney disease (2); endothelial dysfunction (2); fibrosis (2); head and neck squamous cell carcinoma (2); Kabuki syndrome (2); myeloid leukemia (2); Myocardial fibrosis (2); neurological diseases (2); psoriasis (2); viral infections (2); acute pancreatitis (1).
A further 93 diseases each share a sentence with KDM6B in 1 paper.